INS (insulin)
Diseases named in the same sentence as INS in open-access papers (continued):
Sharing a sentence is not in itself a finding about the gene and the disease.
diabetes (continued). "However, if treatment begins after 8 weeks of hyperglycaemia, the administration of insulin normalizes the glycaemia, but does not reverse the structural changes that manifest in the micro and macro complications vascular diseases of diabetes." (PMID 29662261, 2017). "Similar values are consistent with short-term insulin independence in an individual who has not previously ‘failed’ non-insulin therapy but may occur in the DM1 diabetes honeymoon period." (PMID 28663157, 2017). "In some studies, the obvious role of iron overload has been proven in the endocrine glands including pancreas in the pathogenesis of diabetes and other studies have shown that insulin resistance and lack of insulin are the two reasons of pre-diabetes and diabetes in this patients." (PMID 28503277, 2017). "Importantly, insulin secretion was restored when Hdac7-overexpressing beta cells were treated with HDAC inhibitors, supporting the use of such compounds in the treatment of diabetes." (PMID 27796421, 2017). "Therefore, we propose that dynamic insulin sensitivity indicators may reflect metabolic adaptations to usual dietary intakes for maintenance of glucose homeostasis rather than an increase in risk of diabetes, and question their validity in dietary intervention studies." (PMID 29186908, 2017). "However, not all people with insulin resistance develop diabetes, since an increase of insulin secretion by pancreatic beta cells is frequently seen as the disease progresses." (PMID 28070499, 2017). "Mice lacking IRS1 show insulin resistance and growth retardation, but do not develop diabetes because hyperinsulinemia possibly compensates for this resistance, whereas the disruption of IRS2 impairs insulin secretion by the pancreatic β-cells, causing type 2 diabetes." (PMID 28880250, 2017). "Various common comorbidities were assessed in each ethnic group, including coronary artery disease, hyperlipidemia, smoking history, hypertension, diabetes mellitus (both insulin-dependent and non-insulin dependent), and human immunodeficiency virus (HIV) infection." (PMID 28168132, 2017). "Therefore these results suggests that insulin secretion capability, not insulin sensitivity, is a major factor responsible for alcohol-related diabetes onset." (PMID 28779170, 2017). "However, this trend was not seen in South Asians, who already had higher insulin secretion levels 20 years before they were diagnosed with diabetes." (PMID 28409212, 2017). "The pathogenesis of diabetic liver injury has not been fully elucidated, because of insufficient insulin secretion and insulin resistance during diabetes, patients happened to hyperglycaemia, hyperlipidaemia, hyperaminoacidemia based on the disturbance of carbohydrate metabolism." (PMID 29078720, 2017). "The maturity onset diabetes of the young (MODY) is a monogenic form of diabetes characterized by an autosomal dominant inheritance; the onset usually happens before the 25 years of age and is characterized by an impaired insulin secretion with minimal or no defect of the insulin action." (PMID 28116330, 2017). "Lack of insulin is a common consequence of diabetes mellitus type 1." (PMID 28878680, 2017). "In each subgroup, maternal and neonatal outcomes were compared with the population without diabetes, and according to whether or not diabetes was insulin-treated." (PMID 28197657, 2017). "This classification allowed us to analyse outcomes in a large GDM cohort according to whether or not diabetes was insulin-treated and in a second analysis to avoid ‘contamination’ of GDM data by the presence of women with undiagnosed pregestational diabetes." (PMID 28197657, 2017). "It should be noted that association of TGM2 mutations and dysfunction has not been confirmed in larger diabetes patient cohorts so far and TGM2 KO mice have no impairment in glucose-stimulated insulin secretion by pancreatic islets relative to wild-type littermates." (PMID 28248968, 2017).
diabetes (continued). "Fasting saliva insulin concentration was ~30% of the plasma concentration with absolute mU/L values slightly higher, but in the same general range, to those previously recorded in adults without diabetes." (PMID 29099048, 2017). "In fact, a downregulation of approximately 50% of renal Oct1 and Oct2 protein expression was observed four weeks after the induction of diabetes by streptozotocin in male Sprague-Dawley rats, and this downregulation was not prevented by administration of a low-dose insulin treatment." (PMID 28079150, 2017). "The treatment with the purified phospholipids had no noticeable effect on the diabetes-related parameters glycated hemoglobin (HbA1c), glucose and insulin, which is in line with findings in a meta-analysis of human studies on effects of omega-3 fatty acids on diabetes type-2." (PMID 28095913, 2017). "However, the use of non-human forms of insulin to control diabetes is known to lead to both allergic reactions and other complications resulting from antibody production in some patients." (PMID 29086855, 2017). "Ten biochemical parameters related to diabetes and obesity were measured by a multiplex kit: c-peptide, ghrelin, glucose-dependent insulinotropic polypeptide (GIP), glucagon-like peptide-1 (GLP-1), glucagon, insulin, leptin, plasminogen activator inhibitor-1 (PAI-1), resistin and visfatin." (PMID 28915840, 2017). "Since APDs may decrease insulin secretion through blocking M3 receptors on β-cells, it is worth to trial whether a specific M3 agonist could mitigate APD-induced diabetes." (PMID 29209160, 2017). "Last, although no information for medication of dyslipidemia, we found 161 participants with medication for diabetes (including oral medicine and insulin injection) and 287 participants with noncommunicable disease (including dyslipidemia) through questionnaire." (PMID 29272309, 2017). "Diabetes mellitus (DM, ICD-10: E10.900, E11.900) is the most prevalent metabolic disorder that is characterized by chronic sustained hyperglycemia due to defects in insulin secretion from beta cells of the pancreas or resistance against insulin action." (PMID 29381968, 2017). "We found that women who take insulin have likely increased, whereas women taking oral antidiabetic agents or not taking any mediation have strongly decreased breast density, compared to women without diabetes." (PMID 27832382, 2017). "Even when I got diabetes I hoped not to become an insulin user." (PMID 28405339, 2017). "‘Type of diabetes’ may not be accurately recorded in primary care and the increased use of insulin in type 2 diabetes makes ‘insulin usage’ an unreliable criterion." (PMID 28840258, 2017). "Thus, improving systemic insulin sensitivity is effective in controlling diabetes in this model, without a requirement for insulin-replacement therapy." (PMID 28093504, 2017). "The HOMA-IR calculated from fasting plasma glucose level and immunoreactive insulin (IRI) is a simple method for the evaluation of insulin sensitivity and correlates with the results of glucose clamp test in subjects with mild diabetes without significant hyperglycemia." (PMID 28798859, 2017). "The results demonstrated that RBPP-P treatment significantly improved insulin sensitivity to increase glucose uptake, but not RBPP-N, indicating that pectic polysaccharide could benefit to patients with obesity-associated diabetes." (PMID 28452943, 2017). "When information regarding insulin therapy is not sufficiently communicated to a patient’s primary care provider, continuity of care for patients with diabetes may be compromised." (PMID 28852529, 2017). "Significant improvements in treatment satisfaction (DTSQc) were observed at 6 months regardless of treatment modality (MDI or basal insulin only), diabetes type (T1D or T2D), or HCP practice type (specialist or nonspecialist), with a total mean (SD) score of 14.3 ± 5.1, <0.0001." (PMID 29027812, 2017).
diabetes (continued). "In summary, our data demonstrate that insulin inhibits Nrf2 genetranscription and prevents Nrf2 stimulation of intrarenal Agt geneexpression via hnRNP F/K, indicating that Nrf2 activation may amplify renal dysfunctionvia intrarenal RAS activation in diabetes." (PMID 28324005, 2017). "Many of the diabetes studies indicate that inhibition of extracellular IDE activities may be a useful method for treating diabetes, since extracellular IDE can interfere with normal blood glucose transport by decreasing plasma insulin levels within diabetic subjects." (PMID 28070499, 2017). "This suggests that, irrespective of the type of diabetes, the adjunction of an insulin sensitizer to any patient on insulin could be beneficial in terms of reduction of micro or macro-vascular complications." (PMID 29017477, 2017). "A number of factors including irregular supply of insulin, non-availability of structured diabetes programs, and lack of acceptance of chronic diseases within the society (employer/school) may contribute to this difference." (PMID 28606170, 2017). "Similar to the findings of this review, in a review of commercial apps for diabetes self-management, El Gayar found that 12 of 71 (17%) had decision support capabilities and all of them were related to insulin dosage suggestions as opposed to lifestyle changes." (PMID 30291088, 2017). "Low AGE diets were found to decrease insulin resistance in the whole group, decrease total and low density lipoprotein (LDL)-cholesterol in those without diabetes, and decrease fasting insulin and C-reactive protein (CRP) in people with type 2 diabetes (n = 112)." (PMID 29232895, 2017). "As in classical type 2 diabetes, impaired insulin sensitivity and β-cell dysfunction contribute, in this sequence, to progression to IGM and DM." (PMID 29053727, 2017). "The three patients studied were female, presented with recurrent spontaneous hyperinsulinaemic hypoglycaemia (glucose level below 2·5 mmol/l confirmed on laboratory evaluation of venous blood), ‘positive’ insulin antibodies and were not treated for diabetes mellitus at the time of blood sampling." (PMID 27588366, 2017). "A Type 1 diabetic patient, a Type 2 diabetic patient, an individual with pre-diabetes, and a healthy control can all show—under the right circumstances (for example, before or right after eating) completely indistinguishable glucose and insulin amplitudes." (PMID 28439230, 2017). "Since the same study showed a negative association between the use of Insulin and PSA levels (−16%) we analyzed our data to determine if the lower PSA levels could be caused by diabetes alone." (PMID 28239505, 2017). "The disease itself, also called diabetes mellitus, is manifested when there is persistent hyperglycemia in the blood arising from either insufficient (or not at all) amount of insulin released from the pancreatic β-cells and/or resistance to insulin is developed by vital organs." (PMID 29267214, 2017). "While type 1 diabetes mellitus (T1DM) predominantly results from autoimmune destruction of pancreatic β-cells, with little or no insulin synthesis, type 2 diabetes mellitus (T2DM) develops due to the installation of insulin resistance in target tissues, and high circulating insulin levels." (PMID 29053582, 2017). "Diabetes is managed through pharmacologic therapy and lifestyle modifications such as exercise, diet, and glucose monitoring, T1DM is defined by the patient’s inability to produce insulin, and thus, these patients are dependent on the administration of insulin for proper management of the disease." (PMID 30291096, 2017). "Considering these findings, whether or not insulin treatment is appropriate for HCC patients with diabetes needs to be examined." (PMID 28903776, 2017). "The aim of this study is to determine whether breast cancer patients with diabetes have a specific clinicopathological tumor subtype compared to those without diabetes, and whether the use of insulin is related to this." (PMID 28076434, 2017).
diabetes (continued). "However these two studies are not exactly comparable as we studied only insulin-treated diabetics with longer diabetes duration." (PMID 28913365, 2017). "In diabetes, although the blood glucose level is high, polyphagia is increased because the arterio-venous gradient is low as the cells cannot use the glucose due to absence of insulin." (PMID 28077129, 2017). "Down-regulation of Inpp5f in response of decreased insulin signaling activity rescues Akt activity in a negative feedback manner and is cardioprotective in the context of diabetes, while uncontrolled hyperglycemia and hyperlipidemia blocks the protective feedback through upregulating Inpp5f." (PMID 26908121, 2016). "Secondly, T2DM was defined according to fasting plasma glucose level or the use of insulin or anti-diabetic medications during the previous 2 weeks or the participants’ report of previous diagnosis of diabetes by a physician and not by oral glucose tolerance test (OGTT)." (PMID 27510966, 2016). "Computer-based insulin protocols that individually construct patient centered insulin therapies can provide the IR data, which may indicate impending infection if the IR is elevated in patients without diabetes." (PMID 26819233, 2016). "This the first study testing the UK classification guidelines in a large cohort of insulin-treated patients against a gold standard classification of diabetes subtype based on presence or absence of retained endogenous insulin secretion (measured using C-peptide) >5 years post-diagnosis." (PMID 27080317, 2016). "Intensive insulin therapy may be necessary if conventional therapies were no longer sufficient to maintain glycemic control in patients with type 2 diabetes mellitus (T2DM)." (PMID 26839889, 2016). "The mean weight reduction in patients with diabetes was -2.8 kg, which makes GLP-1 RA a preferred option for patients who are obese compared with treatments which may increase weight, including sulfonylureas and insulin." (PMID 27019360, 2016). "Protein tyrosine phosphatase (PTP) expressed in insulin-sensitive tissues (such as liver, muscle, and adipose tissue) has a key role in the regulation of insulin signaling and pathway activation, making PTP a promising target for the treatment of type 2 diabetes mellitus (T2DM) and obesity." (PMID 27561370, 2016). "However, we additionally ran subgroup analysis of patients with and without the requirement of insulin therapy, to identify mortality-related outcomes according to the severity of diabetes." (PMID 27618811, 2016). "After adjusting for age, sex, obesity and diabetes complications, the analysis showed not significant association between bone markers (OC, CTX, P1NP) and metabolic risk factors including FBS, TG, TC, HDL, LDL, HbA1c, and insulin (p > 0.05)." (PMID 27826545, 2016). "Diabetes mellitus is a group of polygenic disorders in which a person has high blood glucose, where insulin production is inadequate, and/or the body's cells do not respond properly to insulin." (PMID 27733237, 2016). "Although insulin is the best therapy for Type-I diabetes and reduce blood glucose level, it possesses prominent side effects and often fails to alter the complications of diabetes." (PMID 27790139, 2016). "However, this study is difficult to compare with ours, because it was not restricted to patients with sepsis and the comparator group consisted of both patients with diabetes mellitus not treated with insulin and patients without diabetes mellitus." (PMID 27495247, 2016). "The diabetic treatments used in the non-metformin group included: sulfonylureas (n = 10), insulin (n = 7), diet control (n = 8), and thiazolidinedione (n = 3), 6 of these subjects changed diabetes treatment before the time of last follow-up, but none changed to metformin." (PMID 26788855, 2016).
diabetes (continued). "Among the participants, insulin was the most commonly used medication for diabetes treatment; 55%, and 53.5% of the individuals had other chronic diseases while 66.7% had no complications of diabetes." (PMID 27904812, 2016). "The early stages of type 2 diabetes mellitus (T2DM) is characterised by postprandial hyperglycemia due to increased breakdown of starch by α-amylase, absorption of glucose by α-glycosidase, insulin resistance and defects with insulin secretion from beta cells of the pancreas." (PMID 27585435, 2016). "Participants were 4,333 male employees (mean age, 49.3 years) who underwent abdominal computed tomography scanning, measured fasting insulin, and did not self-report diabetes and mental disorders under treatment and history of cancer, myocardial infarction, and stroke." (PMID 26891344, 2016). "Only 5.0% of patients were not prescribed any oral diabetes medicine or insulin." (PMID 27583362, 2016). "Diabetes duration and intensity of insulin treatment were not related to weight excess." (PMID 27011769, 2016). "In insulin resistance, diabetes, and overt diabetic nephropathy, IRS2-dependent stimulation of sodium transport by insulin in the PT is preserved and this may induce sodium retention, whereas IRS1-dependent suppression of gluconeogenesis is attenuated and might induce hyperglycemia." (PMID 27247938, 2016). "Vitamin D deficiency has also been suggested to be related to insulin resistance and to the risks of type 2 diabetes mellitus, as well as those of metabolic syndrome, but 25(OH)D values may not correlate with insulin activity or secretion." (PMID 27413370, 2016). "During the development of the type 2 diabetes mellitus rat model, the hypothalamic NPY content and NPY mRNA expression increased in a time-dependent manner, which was positively correlated with the changes of the serum insulin and leptin and negatively correlated with the plasma ghrelin." (PMID 27867820, 2016). "Compared to the non-T2D study population, the diabetes study population (which was heavily influenced by a single study comprising just older people T2D, the ET2DS, n = 1066) had a higher BMI, higher triglycerides, higher blood pressure, fasting glucose, insulin and glycated haemoglobin." (PMID 27549350, 2016). "Thus it is not unlikely that patients whose diabetes was difficult to treat were switched to sulfonylureas or insulin, explaining at least in part higher HbA1C levels in these patients." (PMID 27286816, 2016). "Diabetes worsens the situation, as these subjects not only have more liver fat than healthy subjects but also have increased fasting glucose production and GNG, and impaired suppression of glucose production, GNG and peripheral lipolysis during insulin administration." (PMID 26839171, 2016). "Regarding our third hypothesis, we also identified significant differences between those who had been delegated to administer insulin and those who had not for the general diabetes subscale (P < 0.01)." (PMID 27366112, 2016). "In addition, when recombinant DPP4 is added to adipocytes, it disrupts insulin-mediated phosphorylation of Akt suggesting that overexpression of DPP4 in conditions of obesity and diabetes may result in insulin resistance." (PMID 27213360, 2016). "However, even patients who did not have a history of diabetes had hyperglycemia and needed insulin treatment." (PMID 28031946, 2016). "Finally, although we measured fasting glucose, we did not measure insulin levels, and recently, low AGE diet has been linked to improved insulin sensitivity in diabetes." (PMID 26781037, 2016). "Therefore, the present study was designed to evaluate the effect of an apple polyphenol extract (APE) on insulin sensitivity in obese Zucker fatty fa/fa rats (OZR, an insulin resistant model) as a novel antihyperglycemic mechanism to counteract diabetes progression." (PMID 27141227, 2016).